SLC22A9 (solute carrier family 22 member 9)
Description:
Sodium-independent organic anion transporter, exhibits high specificity for sulfated conjugates of xenobiotics and steroid hormones such as estrone 3-sulfate (E1S) and dehydroepiandrosterone sulfate (DHEAS). Can transport the statin pravastatin and may contribute to its disposition into the hepatocytes when the function of OATPs is compromised. It is specifically activated by 3 to 5 carbons-containing short-chain fatty acids/SCFAs, including propionate (propanoate), butyrate (butanoate) and valerate (pentanoate). May operate the exchange of sulfated organic components against short-chain fatty acids/SCFAs, in particular butanoate, at the sinusoidal membrane of hepatocytes.
Synonyms: OAT7; hOAT4; UST3; OAT4; FLJ23666; UST3H
Tractability: Small molecule: it belongs to a druggable protein family. Antibody: UniProt places it where antibodies can reach, with high confidence; UniProt predicts a signal peptide or a membrane-spanning region; its Gene Ontology location is reachable by antibodies, with medium confidence. PROTAC: ubiquitination databases record sites on it; its protein half-life has been measured.
Target class: SLC superfamily of solute carriers; Electrochemical transporter; SLC22 family of organic cation and anion transporters; Transporter
Gene: Protein-coding gene on chromosome 11 (63,369,725 to 63,410,881, forward strand). Ensembl gene ENSG00000149742.
Subcellular location: Basolateral cell membrane
Gene Ontology:
Molecular function: protein binding; secondary active transmembrane transporter activity; short-chain fatty acid transmembrane transporter activity; transmembrane transporter activity
Biological process: hormone transport; short-chain fatty acid transmembrane transport; sodium-independent organic anion transport; transmembrane transport
Cellular component: basolateral plasma membrane
Genetic constraint (gnomAD): Loss-of-function variants: 54 observed, 46.37 expected, observed/expected ratio (o/e) 1.16, 90% interval 0.94 to 1.46. The upper end of that interval is the gene's LOEUF score, 1.46, which puts it in group 6 of 6, group 1 being the genes least tolerant of losing a copy. Missense variants: 738 observed, 690.52 expected, observed/expected ratio (o/e) 1.07, 90% interval 1 to 1.14. Synonymous variants: 255 observed, 248.55 expected, observed/expected ratio (o/e) 1.03, 90% interval 0.93 to 1.14.
Homologues: Orthologues: chimpanzee SLC22A9 (99% identical), dog SLC22A9 (63% identical), rat Slc22a25 (56% identical), mouse Slc22a19 (55% identical), rat AABR07006120.1 (54% identical), mouse Slc22a27 (54% identical), mouse Slc22a29 (53% identical), mouse Slc22a28 (53% identical), mouse Slc22a30 (53% identical), mouse Slc22a26 (52% identical), rat Ust5r (52% identical), rat UST4r (51% identical), and 51 more. Paralogues in human: SLC22A25 (72% identical), SLC22A24 (56% identical), SLC22A10 (56% identical), SLC22A12 (44% identical), SLC22A11 (42% identical), SLC22A6 (36% identical), SLC22A8 (36% identical), SLC22A7 (30% identical), SLC22A13 (29% identical), SLC22A5 (27% identical), SLC22A4 (25% identical), SLC22A2 (24% identical), and 10 more.
Diseases named in the same sentence as SLC22A9 in open-access papers:
SLC22A9 is named in the same sentence as 8 diseases in open-access papers, as found by Europe PMC text mining. Sharing a sentence is not in itself a finding about the gene and the disease. The quoted sentences say what the papers report.
adenoma (1 paper, 2015). A neoplasm arising from the epithelium. "Such analyses identified three genes (ACVR2A, TGFBR2, and SLC22A9) and an additional two genes (TCERG1 and TRIM59) whose mutations were enriched for clonal and adenoma-specific categories, respectively." (PMID 26336987, 2015).
gout (1 paper, 2022). A condition characterized by painful swelling of the joints, which is caused by deposition of urate crystals. "The rs11231463.G allele of SLC22A9 increased the risk of gout by 2.2 times compared with urate-normal controls in this study." (PMID 35264217, 2022). "Two additional SNP variants (rs2231142.GG of ABCG2 and rs11231463.GG of SLC22A9/OAT7) were selected based on their contributions to gout in the development cohort and their reported effects on renal urate handling." (PMID 35264217, 2022). "To enhance the prediction efficacy of genetic predictors, we selected two additional variations, rs2231142.GG of ABCG2 and rs11231463.GG of SLC22A9/OAT7, based on their contributions to gout in the development cohort and their effects on renal urate handling as reported." (PMID 35264217, 2022).
hepatoma (1 paper, 2016). "This is notably the case for the hepatoma HuH-7 cell line, already used for analyzing regulation of the ABC transporters MRP2, BSEP and P-gp, and of the SLC transporter organic anion transporter (OAT) 7 (SLC22A9)." (PMID 28036031, 2016).
osteoporosis (1 paper, 2020). A condition of reduced bone mass, with decreased cortical thickness and a decrease in the number and size of the trabeculae of cancellous bone (but normal chemical composition), resulting in increased fracture incidence. "Recently, variants in the SLC22A9 gene have been associated with osteoporosis in Korean females." (PMID 33013684, 2020). "We therefore hypothesized that genetic variants in SLC22A9 may be novel biomarkers not only in Koreans but also in Europeans to identify patients at risk for developing osteoporosis." (PMID 33013684, 2020). "We therefore hypothesized that SLC22A9 genetic variants may contribute to the pathophysiology of osteoporosis in Europeans." (PMID 33013684, 2020). "Our results indicate that, in contrast to the situation in Koreans, single SLC22A9 genetic variants apparently do not have a major impact on osteoporosis risk prediction in Europeans." (PMID 33013684, 2020). "Recently, a missense variant in the SLC22A9 gene was identified in Korean females with osteoporosis but not in control subjects." (PMID 33013684, 2020). "Our results indicate that single genetic SLC22A9 variants do not have a major impact on osteoporosis risk prediction in Europeans, yet findings need to be replicated in larger-scale studies." (PMID 33013684, 2020). "Our aim was to assess the association of SLC22A9 genetic variants with bone quality, fracture risk and serum bone turnover markers in a cross-sectional population-based cohort study from Germany (SHIP), which had been previously used to identify fracture risk and risk factors for osteoporosis." (PMID 33013684, 2020).
tumor (2 papers, 2017 to 2018). "Undercoverage of several genes (ACVR2A, ASTE1, KIAA2018, SLC22A9, and TGFBR2) were common events across multiple tumor types, including STAD." (PMID 30281678, 2018). "The most recurrent frameshift MSI events are found in ACVR2A (51.6% of the tumours), KIAA2018 (51%), SLC22A9 (50%), ASTE1 (45%), TGFBR2 (44%), NDUFC2 (36%), LTN1 (36%) and SEC31A (36%)." (PMID 28585546, 2017). "ACVR2A, TGFBR2, KIAA2018, ASTE1 and SLC22A9 frequently harbour MSI events in STAD and COAD, whereas several other genes are mostly specific to a single tumour type." (PMID 28585546, 2017).
cancer (1 paper, 2021). A tumor composed of atypical neoplastic, often pleomorphic cells that invade other tissues. "Six of these genes were not expressed or were very weakly expressed (ABCC11, SLC22A6, SLC22A7, SLC22A8, SLC22A9, SLCO1B1), and among the other eight genes, only gene ABCG2 showed significant difference in expression in cancer versus adjacent control tissue." (PMID 33917029, 2021).
SLC22A9 also shares sentences with these, for which no sentence is quoted: glioma (1 paper); ovarian carcinoma (1).